PF4 (platelet factor 4)
Diseases named in the same sentence as PF4 in open-access papers (continued):
Sharing a sentence is not in itself a finding about the gene and the disease.
Thrombocytopenia (continued). "According to the author’s descriptions, this disorder manifests with atypical thrombotic events (e.g. CVST, SVT) associated with thrombocytopenia 5 to 15 days following vaccination and could be mediated by platelet-activating autoantibodies against platelet factor 4 (PF4)." (PMID 36418321, 2022). "These immune complexes activate platelets via FcγRIIa binding, resulting in thrombocytopenia and platelet activation (see Pathogenesis of thrombosis and thrombocytopenia in anti‐PF4 disorders)." (PMID 40589323, 2025). "Patients present with severe thrombocytopenia, grossly elevated D-dimer, and most test positive for anti-platelet factor-4 antibodies." (PMID 40348868, 2025). "Anti-platelet factor 4 (PF4) immunothrombosis is characterized by thrombocytopenia, thrombosis and enhanced NETosis and has been described in the absence of prior heparin exposure." (PMID 40276517, 2025). "Early detection of transcriptional changes in blood samples during treatment courses positions NFE2 and PF4 as promising biomarkers for proactively monitoring and mitigating treatment-emergent thrombocytopenia." (PMID 40937321, 2025). "This condition was characterized by recurrent thromboses and thrombocytopenia, positivity for the platelet-activating anti-PF4 antibodies, and was defined as monoclonal gammopathy of thrombotic significance (MGTS)." (PMID 40573981, 2025). "These antibodies induce PF4 clustering and platelet activation in a heparin-independent manner, leading to thrombocytopenia and thrombotic complications." (PMID 40276517, 2025). "Simultaneously, thrombocytopenia is mediated by the clearance of anti‐PF4 immune complex‐bound platelets via macrophages of the reticuloendothelial system." (PMID 40589323, 2025). "The underlying mechanism of thrombocytopenia and thrombosis in HIT primarily involves the formation of the PF4-heparin-IgG complex, which binds to the FcγRIIa receptor on the platelet surface." (PMID 40717963, 2025). "The study aimed to determine the pooled incidence of thrombocytopenia and anti-platelet factor (PF)-4 antibody formation among adults exposed to UFH and LMWH." (PMID 41510452, 2025). "This shift occurs through the inhibition of protein C activation and the binding of PF4 to von Willebrand factor, resulting in thrombocytopenia and substantial thrombin generation." (PMID 40276517, 2025). "Anti-PF4-polyanion antibodies drive platelet and neutrophil activation, with thrombocytopenia potentially resulting from direct platelet binding." (PMID 40733710, 2025). "It results from an autoantibody against endogenous platelet factor 4 (PF4) in complex with heparin, which then activates platelets and can cause arterial and venous thrombosis as well as thrombocytopenia." (PMID 41552073, 2025). "These disorders are characterised by the binding of immunoglobulin G (IgG) antibodies to PF4 complexes, leading to platelet activation and consequent thrombocytopenia and thrombosis." (PMID 40589323, 2025). "Nine patients were identified as VITT-like due to unusual thromboses (specifically CVST, SVT, and arterial events), thrombocytopenia, high D-dimer levels, and the presence of anti-PF4 IgG antibodies." (PMID 40573981, 2025). "This case report details a very unfortunate patient with aggressive thrombosis and thrombocytopenia secondary to monoclonal anti‐PF4 antibodies, with functional testing showing cross‐over VITT‐like and HIT‐like activity." (PMID 40298004, 2025). "PF4 binds to anionic molecules to form immune complexes, which promote platelet activation and coagulation, leading to thrombosis and thrombocytopenia." (PMID 40672462, 2025). "I would suggest that for now, just the presence of otherwise unexplained thrombocytopenia and thrombosis should be enough for anti‐PF4 ELISA testing." (PMID 40289696, 2025). "The objective of this study is to determine the pooled incidence of thrombocytopenia and anti‐PF4 antibody formation among adults exposed to UFH and LMWH." (PMID 41510452, 2025).
Thrombocytopenia (continued). "Confounding factors include platelet consumption, blood product administration, hemodilution, and a high rate of anti-PF4/heparin antibody seropositivity (“secondary thrombocytopenia”)." (PMID 40061541, 2025). "Pre-pandemic research on heparin-induced thrombocytopenia (HIT) showed that heparin, a polyanion, binds PF4, triggering anti-PF4-heparin antibodies that activate platelets, monocytes, neutrophils, and endothelial cells, leading to thrombocytopenia." (PMID 40733710, 2025). "VITT after COVID-19 vaccination raised awareness for the co-occurrence of thrombosis and thrombocytopenia as an indication of an anti-PF4 disorder." (PMID 40236285, 2025). "VITT is a rare but severe adverse event characterized by thrombocytopenia and thrombosis, often in atypical anatomical locations, and the presence of antibodies against platelet factor 4 (PF4)." (PMID 38793810, 2024). "This life-threatening condition is characterized by thrombocytopenia, systemic activation of coagulation, and anti-platelet factor 4 antibodies, often resulting in extensive venous thrombosis." (PMID 40729266, 2024). "Thrombocytopenia-associated changes common to both tumor types included an increase in RANTES, EGF, and angiopoietin-like 3 levels, and a reduction in PF4 levels." (PMID 38493157, 2024). "Only 1/71 (1.4%) patient in this study experienced recurrent thrombocytopenia and thrombosis despite anticoagulation, and this patient also tested positive for platelet-activating anti-PF4 antibodies, likely representing a case of persisting VITT." (PMID 38398325, 2024). "PF4 is released in an inflammatory response to thrombocytopenia, primarily by activated platelets, although endothelial cells have been shown to produce PF4 as well." (PMID 38693577, 2024). "HIT is characterized by the development of antibodies against platelet-factor 4 (PF4) bound to heparin after exposure, causing life-threatening thrombocytopenia, arterial thrombosis, and/or venous thrombosis." (PMID 39200826, 2024). "PF4-iDTR mice were administered diphtheria toxin (DT) to induce Mk apoptosis and acute thrombocytopenia for up to 5 days." (PMID 39302653, 2024). "Thrombosis occurs concurrently with thrombocytopenia in the presence of antibodies to platelet factor 4 (PF4)." (PMID 38787838, 2024). "It is believed to involve immune-mediated mechanisms, possibly related to antibodies against heparin-platelet factor 4 complexes, similar to heparin-induced thrombocytopenia." (PMID 38957518, 2024). "From five to thirty days post vaccination, high titers of anti-PF4 IgG antibodies are observed in the circulation, followed by thrombosis and thrombocytopenia." (PMID 37834770, 2023). "A clinical study investigating adverse events (thrombosis and thrombocytopenia) in 23 patients who received a first dose of the ChAdOx1 nCoV-19 vaccine reported induction of auto-antibodies to PF4." (PMID 37243131, 2023). "Amongst others, an unexpectedly high percentage of COVID‐19 patients, clinically suspected to have heparin-induced thrombocytopenia, developed high titers of anti‐platelet-factor-4(PF4)/heparin antibodies." (PMID 35871171, 2023). "VITT is an uncommon prothrombotic syndrome that presents with a constellation of findings that includes venous or arterial thrombosis, mild to severe thrombocytopenia, and anti-platelet factor 4 (aPF-4) antibodies." (PMID 36741657, 2023). "These included clinical variables (degree of thrombocytopenia, timing of thrombocytopenia, etc.), as well as laboratory variables (immunoassay detecting anti-PF4/heparin antibodies, hemoglobin concentration, WBC count, platelet count, etc.)." (PMID 36980370, 2023). "This disorder presents as extensive thrombosis in atypical sites, primarily in the cerebral venous, alongside thrombocytopenia and the production of autoantibody against platelet-factor 4 (PF4, chemokine CXCL4)." (PMID 37759488, 2023).
Thrombocytopenia (continued). "Hematology initially evaluated the patient for disseminated intravascular coagulation, heparin-induced thrombocytopenia (anti-PF4 antibody was 0.19), and thrombotic thrombocytopenic purpura (PLASMIC score of 4)." (PMID 37218820, 2023). "Recently several patients have been identified who presented with a VITT-like syndrome, including thrombocytopenia, thrombosis at unusual sites, high D-dimer levels and PF4-dependent, platelet-activating antibodies." (PMID 37834770, 2023). "Many studies on PF4 have focused on heparin-induced thrombocytopenia, and research has suggested that the formation of IgG specific to PF4-H antibodies is associated with increased mortality rates in patients undergoing hemodialysis." (PMID 37834171, 2023). "The immunological thrombotic thrombocytopenia potentially associated with the ChAdOx1 nCoV-19 vaccine is clinically similar to severe heparin-induced thrombocytopenia when platelet-activating antibodies against platelet factor 4 (PF4) are present." (PMID 36851087, 2023). "The hallmarks of VITT are thrombosis at unusual anatomic sites, such as brain venous sinuses or the splanchnic vein, severe thrombocytopenia with the presence of platelet-activating antibodies targeting platelet factor 4 (PF4), and high D-dimer levels." (PMID 38140195, 2023). "The diagnostic criteria for VITT comprise five domains: onset of symptoms after vaccination; presence of thrombosis; thrombocytopenia; D-dimer levels; and positive anti-PF4 antibodies." (PMID 36992276, 2023). "Vaccine-induced thrombocytopenia thrombosis (VITT) describes a rare clinical syndrome involving both venous and arterial thromboses, thrombocytopenia, and positive anti-platelet factor 4 (aPF-4) antibodies." (PMID 36741657, 2023). "TTS is a rare symptom characterized by acute venous or arterial thrombosis, thrombocytopenia, and positive PF4-heparin ELISA." (PMID 37325662, 2023). "(Section 5.8), in thrombocytopenia, heparin binds platelet factor 4 (PF4) on the platelet surface and together with anti-heparin IgG, the resultant complex promotes thrombin formation." (PMID 40476920, 2023). "In this study, we demonstrated the incidence of anti-PF4/polyanionic antibodies, thrombocytopenia, and thrombosis after vaccination with ChAdOx1 nCoV-19 in a large cohort of Thais." (PMID 37674185, 2023). "In thrombocytopenia, heparin binds platelet factor 4 (PF4) on the platelet surface and this complex in turn binds IgG, an antibody common after heparin administration." (PMID 40476920, 2023). "The proposed mechanism for thrombocytopenia is the synthesis of IgG antibodies against platelet factor 4 (PF4), which activates platelets and blood clots in large venous arteries." (PMID 36841774, 2023). "In VITT, autoantibodies bind to platelet factor 4 (PF4), after which interaction with Fcy receptor IIA causes platelet activation and aggregation, with subsequent thrombosis and thrombocytopenia." (PMID 38140254, 2023). "In these ACE2 and Ang II-independent thrombotic adverse reactions in which thrombocytopenia is almost universal (VITT), the reaction is associated with circulating anti-PF4 antibodies, which generate procoagulant platelets and stimulates NETosis." (PMID 37243131, 2023). "In this study we conducted a prospective cohort study on the incidence of anti-PF4/polyanionic antibodies, thrombocytopenia, and thrombosis after vaccination with the first, second or the third booster doses of ChAdOx1 nCoV-19." (PMID 37674185, 2023). "VITT is a potentially fatal consequence of COVID-19 vaccination in which blood clotting and thrombocytopenia are induced via an immune response to the endogenous protein, platelet factor 4 (PF4)." (PMID 37261122, 2023). "Anti-platelet factor 4 (PF4) antibodies have also been found to correlate highly with a syndrome mimicking anti-heparin-PF4-induced thrombocytopenia in COVID-19, which has also occurred rarely following SARS-CoV-2 vaccination." (PMID 36769320, 2023).
Thrombocytopenia (continued). "Currently, five criteria are used to define VITT, including recent vaccination, thrombosis, thrombocytopenia, elevated D-dimer levels, and positivity of anti-PF4 antibodies." (PMID 36560413, 2022). "We found significantly lower PF4 levels in type 2B patients with persistent thrombocytopenia when compared to patients with intermittent thrombocytopenia or normal platelet counts." (PMID 36165954, 2022). "After performing laboratory analysis, thrombosis with thrombocytopenia was suggested, further confirmed by highly positive anti‐heparin–platelet factor 4 antibodies assay and color Doppler ultrasonography." (PMID 35769629, 2022). "This structural resemblance can also explain the findings of thrombocytopenia and anti-PF4 antibodies in certain SARS-CoV-2 patients." (PMID 34745596, 2022). "Common features (except) were thrombocytopenia, elevated D-dimer levels, and positivity for platelet factor 4 (PF4) antibodies." (PMID 35887982, 2022). "Serological tests using sera from patients who experienced thrombocytopenia and thrombosis after vaccination revealed high reactivity in anti-PF4/heparin enzyme immunoassays and strong platelet-activating antibodies that are positive." (PMID 34629931, 2022). "The pathology of the syndrome involves formation of autoantibodies against platelet factor 4 (PF4) that activate platelets, leading to thrombocytopenia and thromboembolic events of varying severity and location." (PMID 36016324, 2022). "The first case was a woman in the age group 46–50 years presenting with pulmonary embolism, thrombocytopenia, and positive anti-platelet factor 4 antibody assay 9 days after vaccination." (PMID 35727802, 2022). "We also identified that type 2B VWD patients, particularly those with persistent thrombocytopenia, had lower PF4 levels in comparison to type 1 VWD patients." (PMID 36165954, 2022). "Rare cases of thrombocytopenia and thrombosis after anti-COVID-19 adenovirus-associated mRNA vaccines (VITT) due to platelet-activating anti-platelet-factor 4 (PF4)/polyanion antibodies have been reported." (PMID 35746602, 2022). "In HIT, autoantibodies against heparin-PF4 complexes form after exposure to heparin and activate platelets, leading to thrombocytopenia and widespread thrombosis." (PMID 36560433, 2022). "The remaining patient exhibited recurrent thrombocytopenia with persistently high-titre anti-PF4/heparin IgG and positive platelet-activation." (PMID 36352844, 2022). "After vaccination, using sera from patients who experienced thrombocytopenia and thrombosis showed increased reactivity in anti-PF4/heparin enzyme immunoassays and substantial platelet-activating antibodies (positive)." (PMID 34629931, 2022). "The onset of symptoms 5–30 days after vaccination against SARS-CoV2, the presence of thrombosis, D-dimer level > 4000 FEU, thrombocytopenia and positive anti-PF4 antibodies on ELISA." (PMID 35455346, 2022). "VITT is diagnosed clinically by the presence of mild to severe thrombocytopenia, documented evidence or suspicion of thrombosis and positive antibodies against platelet factor 4 (PF4)." (PMID 35891176, 2022). "VITT presents as thrombosis in atypical sites, thrombocytopenia and the presence of autoantibodies against platelet-factor 4 (PF4)." (PMID 35966540, 2022). "The diagnosis of VITT is confirmed if antibodies against PF4 are detectable in patients with an acute thrombotic event and concomitant thrombocytopenia, and prior COVID-19 vaccination with an adenovirus vector vaccine in an appropriate time window." (PMID 35740269, 2022). "The precise pathophysiological link between the vaccine and VITT is unclear, but the thrombocytopenia can be accounted for by antibodies to platelet factor 4, as are present in heparin-induced thrombocytopenia." (PMID 36148046, 2022). "A mechanism similar to heparin‐induced thrombocytopenia was proposed with antibodies to platelet factor 4 (PF4)." (PMID 35846901, 2022).
Thrombocytopenia (continued). "Based on these findings, this syndrome is closely related to heparin-induced thrombocytopenia (HIT), a medical condition characterized by thrombocytopenia, and the presence of antibodies against the Heparin-PF4 complex." (PMID 34745596, 2022). "TTS, which clinically simulate heparin-induced thrombocytopenia, is mediated by platelet-activating antibodies against platelet factor 4 (PF4) and, interestingly, is more frequently observed following the first dose of ChAdOx1 (Vaxzevria)." (PMID 35612613, 2022). "The vast majority of patients have thrombocytopenia, D-dimer elevation, and positive antibodies to platelet factor 4 (anti-PF4 antibody)." (PMID 36275662, 2022). "Findings from 23 patients in United Kingdom who reported thrombosis and thrombocytopenia between 6 and 24 days post-vaccination showed a major lead to likely occurrence of PF4-dependent syndrome following administration of ChAdOx1 COVID-19 vaccine." (PMID 35368622, 2022). "Our findings indicate that anti-PF4 antibodies activate blood cells via FcγRIIa and are responsible for thrombosis and thrombocytopenia in VITT." (PMID 36064843, 2022). "Most of the patients had platelet-activating antibodies directed against platelet factor 4 (PF4), leading to prothrombotic status and thrombocytopenia." (PMID 35444662, 2022). "Patients with VITT have high levels of antibodies to platelet factor 4 (PF4)–polyanion complexes with platelet activating ability, and the mechanism of thrombosis and bleeding resembles that of autoimmune heparin-induced thrombocytopenia." (PMID 36016155, 2022). "Most of the cases presented with thrombocytopenia, elevated D-dimer, and positive titers of IgG antibodies against platelet factor 4 (PF-4)." (PMID 34745596, 2022). "This patient presented with thrombocytopenia, elevated levels of D-dimer, a positive result of anti-PF4 antibodies, and midbrain infarction." (PMID 35453660, 2022). "Like patients with HIT, patients with VITT present with thrombocytopenia (low platelets) and thrombosis (blood clots, often at unusual sites) and have an anti-platelet factor 4 (PF4) antibody which induces platelet activation." (PMID 36064843, 2022). "Patients with TTS develop thrombocytopenia and autoantibodies against platelet factor 4 (PF4); the latter promote blood clot formation." (PMID 36091063, 2022). "Early diagnosis, considering thrombocytopenia and thrombosis in unusual locations together with detection of anti-PF4-autoantibodies, is important to allow prompt treatment and prevent fatalities." (PMID 36551825, 2022). "This platelet activation induces increased release of PF4, which contributes to complex formation with the newly formed PF4 autoantibodies leading to thrombocytopenia, increased platelet aggregation and thrombus formation." (PMID 34887867, 2021). "They shared similar findings: elevated levels of D-dimers, platelet factor 4 antiplatelet antibodies, corona spike protein antibodies, combined with thrombocytopenia." (PMID 33918932, 2021). "In the classic model of heparin-induced thrombocytopenia, the PF4 interaction with endothelial cell HSPGs leads to the removal of antithrombin that is connected to the HSPGs." (PMID 34356644, 2021). "However, anti-platelet agents and anticoagulation, especially heparin, are employed after surgical as well as conservative treatment, and may cause heparin-induced thrombocytopenia when antibodies react with complexes of heparin molecules and platelet factor-4." (PMID 34418967, 2021). "FcγRIIa potently activates platelets when engaged by the Fc of anti-platelet antibodies, including anti-platelet factor 4 (PF4) antibodies which trigger heparin induced thrombocytopenia." (PMID 34759915, 2021). "In conclusion, we can assume a direct involvement of Spike protein, as well as PF4 chemokine and its specific antibodies in the onset of thrombosis and thrombocytopenia that should be investigated as well in in vivo studies." (PMID 34445266, 2021).